APOE (apolipoprotein E)
Diseases named in the same sentence as APOE in open-access papers (continued):
Sharing a sentence is not in itself a finding about the gene and the disease.
cognitive decline (continued). "We have previously reported that an increasing aging, the increased olfactory score, the increased platelet GSK-3β activity, and the ApoE ε4 genotype were correlated with the cognitive decline in T2DM patients." (PMID 34746146, 2021). "Critically, however, declining brain system segregation explained cognitive decline independently of APOE status." (PMID 35382259, 2021). "Two-way interaction of APOE ε4, leisure activities, and subtypes of leisure activity on the cognitive decline between 2008 and 2014." (PMID 34616288, 2021). "Association of APOE ε4, Index of leisure activities (ILA), and subtypes of leisure activity with a cognitive decline between 2008 and 2014." (PMID 34616288, 2021). "The protective effect of leisure activities on cognitive decline was more pronounced in APOE ε4 carriers." (PMID 34616288, 2021). "One study has found an interaction between n-3 PUFA intake and APOE ε4 when investigating cognitive decline." (PMID 33573174, 2021). "In AD, accelerated cognitive decline and an abnormal internal environment, structure, and function of the brain were also found in APOE ε4 carriers." (PMID 34103098, 2021). "APOE ε4 has been strongly suggested as an important predictor of cognitive decline in AD while APOE ε2 has been shown to be protective." (PMID 34353357, 2021). "While the associations between statin treatment and AD have been explored in the past, this study takes a step further to examine the interaction of sex and APOE with cognitive decline." (PMID 33969178, 2021). "A more noteworthy finding that women APOE ε4 carriers showed more prominent cognitive decline than did men APOE ε4 carriers across the AD spectrum." (PMID 33603015, 2021). "Then, to discover the combined effect of sex and APOE ε4 in the AD continuum, we analysed differences in the rate of cognitive decline stratified by sex and APOE ε4 status." (PMID 33603015, 2021). "In clinical AD, Aβ mediates the association of APOE with PHF, which correlates with cognitive decline." (PMID 34502116, 2021). "This exploratory analysis suggests that interventions aiming to increase DHA blood levels to protect against cognitive decline should consider APOE ε4 carrier status." (PMID 34007965, 2021). "Genotyping of selected single-nucleotide polymorphisms in the APOE, ABCA7, SORL1, BIN1, GAB2, and CD33 genes was conducted, and a Bayesian hierarchical model was fitted to analyze the trajectories of cognitive decline among different genotypes." (PMID 34214049, 2021). "The ε4 allele of the apolipoprotein E (APOE) gene is a known genetic risk factor for AD and global cognitive decline in old age." (PMID 33790814, 2021). "The authors report that APOE ε4 carriers present with blood–brain barrier breakdown in the hippocampus and medial temporal lobes leading to cognitive decline." (PMID 34007965, 2021). "Recently, the Zlokovic group has successfully connected the BBB-associated pericyte injury biomarker, soluble PDGFRβ, in cerebrospinal fluid (CSF) to cognitive decline in apolipoprotein E (APOE4) carriers even after controlling for Aβ and tau status." (PMID 34630020, 2021). "Utilizing similar techniques of large-scale transcriptome gene profiling, we have previously shown the effect of lipid stress and a Western diet (WD) on hippocampal microvascular injury and cognitive decline in male and female mice ApoE-/- and LDL-R-/- mice." (PMID 34836168, 2021). "Recent genetic studies have also indicated that ApoE haplotypes are also related to PD and other neurodegenerative conditions and are responsible for the cognitive decline in these patients." (PMID 33804213, 2021). "Data from the Seattle Longitudinal study spanning over a 21-year period revealed that hypertension synergises with the effects of APOE ε4 on the rate of cognitive decline." (PMID 34867762, 2021).
cognitive decline (continued). "In a population-based cohort study HbA1c of 6.2% or greater predicted faster cognitive decline in individuals aged between 65 and 88 even after adjusting for age, sex, education, and APOE ε4 status." (PMID 34867762, 2021). "Aside from APOE, common variants in MAPT,1,41–43COMT,24,42BDNE, MTHER, and SORL144 have been reported to influence cognitive decline (reviewed in Fagan and Pihlstrom45)." (PMID 33111402, 2021). "A longitudinal study of cognitive decline in older adults used a panel of 8 blood-based markers, including APOE, plasma amyloid β 42/40 ratio, telomere length, serum glucose, cystatin C, C-reactive protein (CRP), interleukin-6 (IL-6), and albumin." (PMID 33946285, 2021). "In AD, SMAD2 is also a part of the TGFβ/SMAD2/STAT3 signaling pathway which is activated by APOE, the important risk factor for AD, and increases the amyloidogenic processing of APP leading to Aβ formation and contributes to cognitive decline." (PMID 34502116, 2021). "We were unable to confirm this in our study, but longitudinal data from HAALSI’s second wave of data collection will enable the assessment of the effects of APOE on age-related cognitive decline." (PMID 34721516, 2021). "The relationship between APOE ε4 carriage and the rate of cognitive decline in AD patients has been examined in several studies." (PMID 34214049, 2021). "This analysis, therefore, highlights, in addition to cognitive decline, adiposity and alanine aminotransferase as potentially having close links with AD pathology given the timing of the effect of APOE-ε4 on them." (PMID 34301914, 2021). "Recent studies have found that the APOE ε4 allele is associated with Aß elevation and accumulation on PET, whereas PRS is more associated with faster cognitive decline in amyloid-positive status." (PMID 34465370, 2021). "The carriage of the APOE ε4 genotype and the G allele in ABCA7 rs3764650 were significantly associated with an earlier midpoint of cognitive decline." (PMID 34214049, 2021). "The association of APOE ε2 (APOE2) allelic dosage with cognition, generally found protective against cognitive decline, also remains under-studied especially in terms of race- and sex effect modifications." (PMID 34193248, 2021). "Unlike those studies, our findings suggest that a well-defined AD PRS can predict cognitive decline over and above APOE ɛ4 at an early stage of AD." (PMID 34615922, 2021). "Our findings further suggest that women APOE ε4 carriers had a steeper cognitive decline than did men APOE ε4 carriers throughout the entire AD spectrum." (PMID 33603015, 2021). "This study investigated the prevalence of apolipoprotein E (APOE) genotypes and cardiovascular disease as risk factors associated with cognitive decline." (PMID 32101309, 2020). "But there were greater cognitive declines in APOE ε4 carriers than non- ε4 carriers among the demented participants." (PMID 31919381, 2020). "The current study demonstrates novel associations between clinician-derived MCI severity stages and APOE-ε4 status, CSF biomarkers of AD pathology and neurodegeneration, cerebral atrophy in regions vulnerable in AD, and cognitive decline." (PMID 32581762, 2020). "Particular interest, herein, deserves the observation that the protective effect of p.P522R can apparently counteract the deleterious effect of APOE-ε4 on cognitive decline for several years and on tau pathology in MCI." (PMID 32166339, 2020). "The present study uses a combination of a longitudinal study design, and assessments of cognition, olfaction and genetics, to enable conclusions regarding relationship among olfaction, ApoE, and 6-year cognitive decline." (PMID 31760549, 2020). "In that case, the results suggest that the PRS-LOAD predicts cognitive decline over and above APOE ɛ4 at a very early stage of AD progression." (PMID 32709845, 2020). "This includes the effect described here for the APOE-ε4 allele and p.P522R in PLCG2 on the cognitive decline." (PMID 32166339, 2020).
cognitive decline (continued). "Another major finding was that APOE e4 genotyping is one of the most predictive factors of cognitive decline from SMI to L-aMCI while once patients progress to clinically manifest AD, the effects of APOE e4 genotyping disappeared." (PMID 32770103, 2020). "To directly compare the protective effect of PLCG2 with that of APOE, we expressed the APOE effect on cognitive decline in protective terms, i.e., cognitive changes when APOE-ε4 is absent." (PMID 32166339, 2020). "In the pooled adjusted analysis, APOE ɛ 4 carriers had higher odds of cognitive decline (odds ratio [OR] = 1.46, 95% confidence interval [CI]: 1.29, 1.64) compared to noncarriers and the results were similar across cohorts (I2 = 19%, p = .29)." (PMID 32110803, 2020). "Typically, longitudinal studies of the effect of APOE on cognitive decline use linear mixed models of data collected from a variety of neuropsychological tests." (PMID 33488674, 2020). "Moreover, increased hypertension was strongly associated with elevated Aβ deposition in healthy aging with at least 1 APOE ε4 allele and AD patients and, together with obesity, could moderate the relationship between Aβ deposition and cognitive decline even in midlife." (PMID 32726298, 2020). "The interaction effect between poor odor identification ability and ApoE-ε4 in predicting future cognitive decline fits well with what is known about regional accumulation of AD neuropathology in preclinical stages." (PMID 31760549, 2020). "Together, these studies show that the APOE genotype has an impact on cognitive decline following chemotherapy." (PMID 33352780, 2020). "In this study, we emphasize that both APOE and PRS are predictors of AD risk presenting age-dependent effects on progression to cognitive decline." (PMID 32464432, 2020). "Although our model shows high accuracy of cognitive decline when trained on cognitive data, there is a substantial gain in predictive efficacy when adding baseline data on APOE 4 status or grey matter density (PLS derived grey mater scores)." (PMID 32106025, 2020). "Most studies finding cognitive decline effects in APOE ε4 carriers have investigated elderly samples from 60 years upwards." (PMID 31191441, 2019). "Other studies, however, have yielded contrary findings, reporting that the protective effects of physical activity on future cognitive decline was specific to APOE ε4 carriers." (PMID 31024289, 2019). "The interaction between sex and ApoE ε4 carrier status on cognitive decline remains an area of intense investigation." (PMID 31410194, 2019). "Although numerous studies suggest potential interactions between various vascular conditions and APOE e4 on cognitive decline, few have examined interactions with high blood pressure, particularly with consideration to antihypertensive medication use." (PMID 31697783, 2019). "The association between APOE ε4 and cognitive decline has been demonstrated in AD, MCI, and normal aging in many studies, and the protective outcome of APOE ε2 on cognitive decline has been observed in AD patients." (PMID 32226373, 2019). "This includes beta-amyloid, which accumulates in apolipoprotein E (APOE) ε4 genotype carriers and contributes to synaptic degeneration and cognitive decline." (PMID 29370207, 2018). "In conclusion, diabetes triggers the disruption of the BBB and increase of APOE and ultimately aggravates cognitive decline through metabolite imbalance due to glymphatic pathway dysfunction." (PMID 30429819, 2018). "The CPO-Aβ17-21P peptide ameliorates AD-related cognitive decline in APPswe/PSEN1dE9 (APP/PS1) transgenic mice by inhibiting Apolipoprotein E (apoE) and Aβ binding, reducing amyloid deposition, and regulating the inflammatory response." (PMID 30352982, 2018). "Three isoforms of ApoE (ApoE2, ApoE3, ApoE4) exist in humans, and their relative expression levels impact HIV-1 infection, HIV-1/AIDS disease progression, and cognitive decline associated with HIV-1-associated neurocognitive disorder." (PMID 29558961, 2018).
cognitive decline (continued). "The spread of tau pathology is related to atrophy and cognitive decline, but little data exist on the effects of APOE ε4 on tau." (PMID 30086796, 2018). "Studies of older adults have reported that higher cortisol levels more strongly predict decrements in contemporaneously measured cognitive ability and subsequent cognitive decline in APOE E4 carriers." (PMID 29451880, 2018). "Note that another study using this sample found that APOE E4 carriers had a lower level of initial cognitive ability and greater cognitive decline." (PMID 29451880, 2018). "The cognitive decline due to microvascular lesions is exacerbated by APOE ε4 and is largely attributed to progression and development of microvascular lesions." (PMID 30232255, 2018). "Our systems-level analysis suggests other potential mediators of the ApoE effect on cognitive decline." (PMID 30618606, 2018). "Longitudinal studies have shown that the APOE ε4 allele, the H1 haplotype in MAPT and mutations in the GBA gene are associated with a more rapid cognitive decline in PD." (PMID 29692703, 2018). "Some researchers argue that the relationship between the ApoE ε4 allele and cognition across the life span is an example of antagonistic pleiotropy, meaning that the ApoE ε4 allele may be beneficial at an earlier age and may become a risk factor for cognitive decline in later life." (PMID 28706481, 2017). "Specifically, genetic polymorphisms of APOE,16BDNF Val66Met,17KIBRA,18COMT Val158Met,19 and SERT 5-HTTLPR20 have each been reported to impact upon later-life cognitive performance, risk of cognitive decline, or brain plasticity." (PMID 30631459, 2017). "APOE effects in the context of disparate patterns of cognitive decline by race present an additional confounder that cannot be addressed in detail by this study." (PMID 28948085, 2017). "The apolipoprotein E (APOE) ε4 allele is a risk factor not only for AD, but also for cognitive decline, depressive symptoms, stroke, hypertension, coronary heart disease, cardiovascular disease, and diabetes." (PMID 27168072, 2016). "In a regression analysis including age, sex and APOE status in the model, there was a weak association between YKL-40 and rate of cognitive decline in the AD cohort." (PMID 27845782, 2016). "Our work underscores the importance of connecting ApoE genotype and insulin sensitivity as an early marker for AD-related cognitive decline." (PMID 27189808, 2016). "On the other hand, our study makes up for some of these limitations by comprising ApoE genotyping of almost the entire sample and CSF biomarkers for about half of the sample, which have strong influence on the evolution of the cognitive decline." (PMID 31022805, 2016). "Firstly, we tested the statistical effects of CSF proteins (n = 83) to measures of brain atrophy, CSF biomarkers, ApoE genotype and cognitive decline." (PMID 26284520, 2015). "Using RS-fMRI, previous study showed that alterations in functional connectivity within the default mode network (DMN) and the executive control network (ECN) are present even before cognitive decline and brain atrophy in middle-aged APOE-ε4 carriers." (PMID 26053677, 2015). "Further, the current results support the growing number of studies reporting the synergistic effect of APOE and Aβ in affecting cognitive decline in preclinical AD." (PMID 26430784, 2015). "Given that ε4 carriage increases the risk of Aβ+ it is likely in these studies that the effect of APOE ε4 on cognitive decline is mainly due to the interaction between Aβ and ε4 rather than an effect of ε4 by itself." (PMID 26430784, 2015). "In this study we aimed to discover CSF proteins associated with AD pathophysiology by testing the multiplex panel with established neuroimaging measures, CSF biomarkers of AD, Apolipoprotein E (ApoE) genotype and cognitive decline." (PMID 26284520, 2015).
cognitive decline (continued). "The aim of the current study was to characterize APOE ε4-related acceleration of Aβ-related cognitive decline over an 18-month test-retest interval on a computerized cognitive battery in a large group of CN older adults whose ε4 and Aβ status was known." (PMID 26430784, 2015). "Individuals in the APOE ε4+/high g-score group exhibited the greatest cognitive decline over time (p<.0001)." (PMID 26102276, 2015). "Even in clinically normal elderly, there is evidence that APOE genotype affects likelihood of cognitive decline, and affects brain structure and function as measured by structural and functional neuroimaging, and neuropathology." (PMID 25738563, 2015). "Baseline tau/Aβ1–42 ratio was associated with rate of cognitive decline on RAVLT (P=4.8510 × 10−5), but there was only a trend for ApoE (P=0.066)." (PMID 25988319, 2015). "Our results are compatible with epidemiological studies that have examined the joint effects of PA and APOE-ε4 inheritance on the extent of cognitive decline and the diagnosis of AD." (PMID 24795624, 2014). "We have previously shown that APOE-ε4 status in healthy elders, in combination with measures of hippocampal atrophy obtained at study entry, can predict future cognitive decline after as short an interval as 18 months." (PMID 24795624, 2014). "One such study reported reduced odds for experiencing cognitive decline in physically active older male APOE-ε4 carriers compared to sedentary carriers." (PMID 24795624, 2014). "We have previously reported, in a sub-sample of the current study, that physically active APOE-ε4 carriers had significantly reduced odds of cognitive decline over 18 months compared to physically inactive carriers." (PMID 24795624, 2014). "The interaction between neurodegenerative diseases such as AD and ApoE genotype on rate of cognitive decline have been extensively studied, but the findings are inconsistant." (PMID 25071563, 2014). "A significant interaction was found between APOE-ε4 carrier status and use of hormone therapy on long-term cognitive decline." (PMID 23418430, 2013). "The current longitudinal findings demonstrate that APOE-ε4 carriers exhibit pronounced TL attrition over just a 2-year window and the data suggest that HT, begun at the onset of the menopausal transition, might buffer against cell aging specifically in women at risk for cognitive decline." (PMID 23418430, 2013). "Reports of interactions between other factors, like physical activity and APOE genotype, demonstrate further complexity to the etiology of late-life cognitive decline." (PMID 23799051, 2013). "Schuit and colleagues were the first to report an interaction between PA and APOE genotype on cognitive decline." (PMID 24961307, 2013). "If apoE is an amyloid catalyst, then reducing apoE levels or function in the brain should result in reduced amyloid deposition and reduced cognitive decline." (PMID 22844635, 2012). "If on the other hand, apoE is involved in Aβ clearance with human apoE4 being a greater inhibitor of clearance (or poorer clearer), then reducing apoE levels or apoE binding to Aβ should increase amyloid deposition and cognitive decline." (PMID 22844635, 2012). "Further investigations, particularly long term longitudinal studies, are necessary to establish if ApoE levels are potential plasma biomarkers of cognitive decline, MCI or AD." (PMID 22701550, 2012). "The apolipoprotein E (APOE) gene is the best-documented genetic risk factor for AD, with the ε4 allele significantly increasing the risk for AD and cognitive decline." (PMID 22028967, 2011). "Among APOE ε4 carriers there is evidence of atypical brain activity in young adulthood and greater cognitive decline in middle-age." (PMID 20515477, 2010). "Follow-up studies are necessary to answer the question of the predictive value of cognitive decline in patients with APOE ε4 in Nordic samples and characteristics of different developmental pathways." (PMID 17974013, 2007).